ANXA1 (annexin A1)
Diseases named in the same sentence as ANXA1 in open-access papers (continued):
Sharing a sentence is not in itself a finding about the gene and the disease.
tumor (continued). "Notably, we found that ANXA1 expression was positively correlated with the tumor volume of PTC patients." (PMID 33531975, 2021). "Moreover, it has recently been shown that tumor growth and metastasis are significantly decreased with the use of AnxA1-KO mice, suggesting the key role of AnxA1 in metastasis formation." (PMID 34681580, 2021). "Thus, Gege3 appeared an attractive molecule able to prevent the paracrine effects of PC cells deriving ANXA1 in the tumor microenvironment." (PMID 34944403, 2021). "In this way, the anti-cPLA2 activity of AnxA1 is abolished and cPLA2 can promote tumor growth." (PMID 34208346, 2021). "Thus, the development and use of effective inhibitors of Annexin A1 signaling would help better understand the role of Annexin A1 in tumor biology." (PMID 34943928, 2021). "ANXA1 has been negatively correlated with increasing tumour grade in OSCC." (PMID 32054041, 2020). "Previously published data on anxA1 expression in tumor vasculature has established the presence of a membrane-bound, N-terminal–truncated form of anxA1 on the luminal membrane of tumor-associated endothelium, and anxA1 has been proposed as a vascular antitumor target." (PMID 32497150, 2020). "Annexin A1 is expressed specifically on the tumour vasculature surface." (PMID 32921792, 2020). "These JX-infected, dying tumor cells released DAMPs, such as calreticulin and annexin A1, which are involved in the activation of DCs.41 42 Additionally, JX itself further induced the activation and maturation of DCs within TME because it was genetically engineered to secrete mGM-CSF." (PMID 33199510, 2020). "ANXA1 expression is therefore varied depending on tumor type." (PMID 33291071, 2020). "This suggests that ANXA1’s oncogenic role in BrC may be attenuated in tumours expressing HR, and that its expression may be more relevant in HER-2+ (non-luminal) tumours." (PMID 33276477, 2020). "We hypothesise that IF7 in tumour stroma actively targets Anxa1 peptides on the tumour cell surface exhibiting the MC16 domain." (PMID 32921792, 2020). "ANXA1 may function as either a tumor suppressor or a tumor promoter, depending on the type of tumor cells/tissues." (PMID 32226026, 2020). "Thus, the importance of the axis ANXA1/EVs-FPRs in PC progression was assessed from a different point of view, and specifically considering the interplays between tumor cells and stroma." (PMID 33353163, 2020). "Of 80 human tumor samples, 30 exhibited 2–3+ staining for anxA1 in the intratumoral vessels." (PMID 32497150, 2020). "Therefore, there is a need to generate anti-anxA1 monoclonal antibodies for IHC study and in vivo tumor uptake study." (PMID 32497150, 2020). "ANXA1 is involved in the immunosuppressive mechanism in tumor-bearing hosts and may be used in a new strategy involving the use of the host's own immunity to achieve tumor suppression." (PMID 32226026, 2020). "Alternately, as a substrate protein of EGFR, ANXA1 may contribute to neoplasm growth via autocrine and paracrine effects and sustain the preinvasive properties of malignant cancers through autocrine signaling induced by the N-terminal peptide." (PMID 32226026, 2020). "On the basis of these data, it appears that tumor uptake of anti-anxA1 antibodies may be dependent on the tumor model or involves the engagement of specific epitopes that are not addressed by these antibodies." (PMID 32497150, 2020). "In tumor development, ANXA1 can be considered as a tissue-specific oncogene or oncosuppressor." (PMID 33353163, 2020). "In addition, enhanced production of annexin A1 in radiotherapy-stimulated MSC can relay anti-tumor signals." (PMID 33023058, 2020). "In addition, ANXA1 appears to have a distinct tumour promoting effect by binding and activating FPR1, the expression of which is shown to be elevated in many tumours." (PMID 33057069, 2020).
tumor (continued). "Immunohistochemistry (IHC) studies have demonstrated that anxA1 is upregulated in several tumor types, including melanoma, hepatocellular carcinoma, gastric cancer, and non–small-cell lung carcinoma (NSCLC), and is downregulated in prostate cancer and many head and neck cancers." (PMID 32497150, 2020). "In conclusion, we used phage panning techniques to isolate anti-anxA1 antibodies with binding profiles designed to target anxA127-346, a truncated form of anxA1 that had previously been identified on the luminal surface of tumor endothelium." (PMID 32497150, 2020). "On the contrary, tumours with ANXA1 expression seem to also exhibit higher ARID1A protein levels." (PMID 33276477, 2020). "ANXA1 is involved in the immunosuppressive mechanism of tumor-bearing hosts and can be used as a new strategy involving the use of the host's own immunity to achieve tumor suppression." (PMID 32226026, 2020). "Intravenously injected IF7 targets tumour vasculature via annexin A1." (PMID 32921792, 2020). "To identify translatable rodent tumor models that could be used to study tumor vascular anxA1 expression, we also used IHC to assess vascular and neoplastic anxA1 expression in several rodent models of cancer." (PMID 32497150, 2020). "Furthermore, tumor cell death leads to the release of immunostimulatory molecules such as ATP and Annexin A1 able to recruit DCs in the tumor microenvironment." (PMID 32580431, 2020). "Additionally, ANXA1 was described as being up-regulated in the tumor neovascular endothelium, and targeting ANXA1 with antibodies resulted in the improvement of the overall survival and response to radiotherapy." (PMID 31357616, 2019). "To investigate whether Anxa1 knockdown impacts on tumor cell proliferation in vivo, we injected them subcutaneously into flanks of C57BL/6 mice (n = 5 mice per group)." (PMID 31545917, 2019). "Other authors reported that ANXA1 plays an important role in the tumor microenvironment." (PMID 31461932, 2019). "Several studies indicate that annexin A1 might function either as a tumor suppressor or a tumor promoter depending on the type of cancer cells." (PMID 31861640, 2019). "Therefore, it is believed that the downregulated expression level of ANXA1 in drug-resistant cell lines leads to a decrease in tumour cell apoptosis, which further reduces the sensitivity of tumour cells to drugs and leads to resistance." (PMID 31949471, 2019). "Furthermore, it has been previously shown that ANXA1 has lower expression in luminal than basal tumor types, confirming its identification as a biomarker by inteGREAT." (PMID 29971090, 2018). "Anxa1-KO mice exhibit a defect in angiogenesis and strongly impaired tumor growth." (PMID 30213070, 2018). "It is known that ANXA1 is differentially expressed in various tumours and it might specifically function as either suppressor or promoter of neoplastic development." (PMID 30518142, 2018). "Thus, ANXA1 has the potential role of biomarker for diagnosis, treatment, and prognosis of certain tumours." (PMID 30518142, 2018). "These genes likely function as downstream effectors of STAT3 in GBM to regulate not only cell proliferation (e.g., GAS7, IGFBP2, MEOX2 and MXI1), and but also tumor-stroma interactions by modulating protein secretion (e.g., ANXA1, ARL4C, EMILIN1, EMP2, EXTL3 and PDIA4)." (PMID 29774125, 2018). "The direct role of AnxA1 on angiogenesis has not been described, as data regarding AnxA1 on angiogenesis were obtained in in vivo and in vitro tumorigenesis conditions, and data suggest that the tumor microenvironment is determinant to angiogenic actions of AnxA1." (PMID 30250432, 2018). "As such, ANXA1 functions to enable antigen uptake and cross presentation of tumor antigens." (PMID 29666625, 2018). "Annexin-a1 is a multifunctional molecule involved in a range of cellular signal transduction pathways, particularly in inflammation, innate and adaptive immune system, tumour progression and metastasis." (PMID 29263330, 2017).
tumor (continued). "ANXA1 plays an important role in tumour development and progression of basal-like breast cancer." (PMID 29263330, 2017). "From these evidences, ANXA1 is suggested to act as a tumor suppressor gene." (PMID 29091952, 2017). "Furthermore, our in vivo experiments confirm the ability of tumor microenvironment or host ANXA1 to control tumour growth and metastasis." (PMID 29263330, 2017). "Therefore, we created orthotopic xenografts with WT, PGS and ANXA1 KO MIA PaCa-2 cells in SCID mice which keep stroma-derived ANXA1, to investigate in vivo the relevance of intracellular ANXA1 in tumour progression." (PMID 27412958, 2016). "Results from these two studies suggest that ANXA1 is a tumor suppressor." (PMID 27941907, 2016). "Annexin A1 an anti-inflammatory and calcium-dependent protein of the superfamily of annexins, may have important regulatory roles in tumor development and progression." (PMID 27034760, 2016). "Thus, annexin A1 seems to play an oncogenic role in some cancers and a tumor-suppressive role in others in a context specific manner." (PMID 26000884, 2015). "Nevertheless, conflicting datasets exist that suggest ANXA1 over-expression in this tumor." (PMID 26312765, 2015). "And, ANXA1 participate in tumor irradiation resistance in NPC via regulating cell apoptosis." (PMID 26196246, 2015). "ANXA1 expression was scored based on the percentage of immunohistochemical staining in tumor cells." (PMID 26137966, 2015). "ANXA1 expression has been reported to be deregulated in tumor development and progression, but the exact mechanisms remain unknown." (PMID 26000884, 2015). "However, when viewed through the lens of tumor subtype, the full relevance and impact of annexin A1 becomes clear." (PMID 26000884, 2015). "ANXA1 expression is “tumor-specific” and might play a multifaceted role in cancer development and progression." (PMID 25038797, 2014). "ANXA1 may contribute to the regulation of tumor growth and metastasis through paracrine mechanisms that are mediated by FPR2/ALX." (PMID 25490767, 2014). "We showed that ANXA1 protein may control tumor growth in a paracrine manner that is mediated by the receptor FPR2/ALX." (PMID 25490767, 2014). "Integration of the in vivo and in vitro data showed that ANXA1 may be effective in the regulation of tumor growth and metastasis through paracrine mechanisms mediated by FPR2/ALX." (PMID 25490767, 2014). "Dysregulation of ANXA1 has been reported in multiple neoplasms, suggesting that this protein may play important roles in tumor development and progression." (PMID 25490767, 2014). "In vivo, annexin A1 prevents the induction of antigen-specific cytotoxic T cell responses and, consequently, impairs anti-tumor immunity and tumor rejection after vaccination against tumor antigens." (PMID 23638088, 2013). "In tumor cells, calcium and other factors may be altered, resulting in an abnormal location of AnxA1." (PMID 23431236, 2013). "Annexin A1 expression can potentially be used as a predictive biomarker to select OSCC patients with moderate/poorly differentiated tumor who may benefit from TPF induction chemotherapy." (PMID 23786757, 2013). "In patients with moderate/poorly differentiated tumor, low Annexin A1 expression benefited from TPF induction chemotherapy in OS (P=0.078, HR=0.410) and DMFS (P=0.048, HR=0.373); however, patients with high Annexin A1 expression did not benefit from TPF induction chemotherapy." (PMID 23786757, 2013). "Consequently, annexin A1 on apoptotic cells compromises antigen-specific anti-tumor immunity and tumor rejection after vaccination against tumor antigens." (PMID 23638088, 2013). "Furthermore, deregulation of ANXA1 has been correlated with tumor progression in several types of cancer." (PMID 23341933, 2013). "Previous research indicated that Anxa1 was upregulated on the tumor endothelium." (PMID 24312470, 2013).
tumor (continued). "However, a subgroup analysis showed that in the patients with moderate/poorly differentiated tumor, low Annexin A1 expression did have an OS and DMFS benefit from TPF induction chemotherapy." (PMID 23786757, 2013). "Thus, RIF7 deserves further research into its capacity as a drug delivery vehicle that targets Anxa1 which is over-expressed on the surface of the tumor vasculature." (PMID 24312470, 2013). "Furthermore, we identified the molecules that were responsible for those over-represented biological processes to reveal an interactome in tumor stroma with annexin A1 being a key functional player." (PMID 23077482, 2012). "The growth of tumor often faced up with lackness of blood and oxygen, and it has been reported that Annexin A1 may be involved in tumor." (PMID 22613333, 2012). "Furthermore, ANXA1 may represent a potential therapeutic target in non-small cell lung cancer, considering that its silencing leads to suppression of tumor cell proliferation, invasion, and migration." (PMID 41283264, 2025). "The comparative analysis of tumor tissues and adjacent margins has also shown a stronger ANXA1 expression in cancer samples (p = 0.0001), in correlation with elevated CEA serum levels (p = 0.004), suggesting that ANXA1 may play a key promoter role in CRC aggressiveness and disease progression." (PMID 41283264, 2025). "Additionally, ANXA1 could impact the function of T cells and dendritic cells, further attenuating the antitumor immune response and supporting tumor growth and survival." (PMID 40744683, 2025). "AXL in GAS6 - AXL ligand-receptor pairs, implicated in HGSOC drug resistance, was exclusively expressed in HLA TAM1 and HLA TAM2, and only monocytes could communicate with tumor cells through ANXA1–FPR, which serve as effective mediators in controlling inflammatory responses." (PMID 40036264, 2025). "Furthermore, peptides common to both ND and R T0 saliva could depict the consistent peptidomic profile of the tumor independently of disease state, namely, the H1-2 fragments and the fragment of ANXA1, the latter shared in addition by NDT1 saliva." (PMID 41155285, 2025). "FPR2 also contributes to fibroblast homeostasis through ANXA1-mediated signaling within the tumor microenvironment (TME), and disruption of this axis facilitates the transformation of fibroblasts into cancer-associated fibroblasts (CAFs), contributing to tumor progression." (PMID 41376620, 2025). "Notably, PYGO2, UBQLN4, and ANXA1 have been associated with responsiveness to tumor immune checkpoint blockade (ICB) therapy, while B4GAL and MDM2 are implicated in regulating CD8 + T cell function and tumor growth." (PMID 38834869, 2024). "Importantly, the ANXA1:FPR1 interaction has been implicated in the tumor microenvironment of several malignancies, indicating that the E. faecalis-infected wound niche mimics the anti-inflammatory transcriptional program of the tumor microenvironment." (PMID 38767331, 2024). "However, the function of ANXA1 seems to be distinct in different or even the same tumor." (PMID 36678567, 2023). "Interestingly, honokiol promoted the up-regulation of ANXA1 while exerting its anti-tumor role, in turn leading to drug resistance that may also be related to hypoxia induction." (PMID 36678567, 2023). "In addition to mediating inflammatory responses, ANXA1 is involved in the development of multiple tumors, metastasis and drug resistance and may be used as a potential biomarker for tumor diagnosis, treatment, and prognosis." (PMID 36988561, 2023). "As ANXA1 seems to be expressed differently across a range of cancers, and this expression also seems to vary depending on factors such as tumour stage and metastasis, the idea of developing this protein as a biomarker for all cancers could be seen as slightly challenging." (PMID 35146757, 2022).
tumor (continued). "Moreover, it will be particularly interesting to amplify the assessment on the impact of EVs with and/or without ANXA1 on co-culture spheroids generated in association with other cell populations surrounding the primary tumor, such as stromal cells." (PMID 36230687, 2022). "Thus, we used WT and ANXA1 KO models to investigate the role of this protein in the generation and growth of spheroids and their pharmacological response, both in basal conditions and by mimicking a tumor system through the addition of autocrine EVs." (PMID 36230687, 2022). "We sought to determine whether ANXA1 could affect tumor growth in vivo." (PMID 34991599, 2022). "In addition, it has been reported that ANXA1 is closely related to tumor development and invasion." (PMID 35711921, 2022). "Thus, we may conclude that CTHRC1 may induce tumor associated macrophage infiltration though GRN/TNFRSF1A and AnxA1/FPR1 pathways." (PMID 35928443, 2022). "Moreover, BLCA cells with ANXA1 knockdown may have other compensatory mechanisms to counter tumor suppression." (PMID 34991599, 2022). "However, studies on the TNF-α/TNFR1/ANXA1 axis with respect to tumours are rare." (PMID 35415239, 2022). "Hence, these data indicate that RRM2 independent role of ANXA1 may also be important for RCC tumor growth." (PMID 34319001, 2021). "Moreover, we also noticed that tumor cells are highly expressed in the ANXA1 gene." (PMID 34912807, 2021). "Immunohistochemical staining was correlated with Fuhrman nuclear grade (an independent predictor of cancer-specific survival), amount of eosinophilic cells and higher clinical stage leading to the conclusion that that Annexin A1 could serve as a prognostic marker for tumor progression." (PMID 34943928, 2021). "Moreover, since ARID1A and ANXA1 contribute to poorer prognosis and pre-exist in treatment-naïve tumours, they may assist in identifying which HER-2+ patients might require a different therapeutic approach." (PMID 33276477, 2020). "Moreover, although we recognise that it would be ideal to analyse many of these phenotypes in Anxa1-deficient mutant mice, we were unable to pursue this strategy because tumours do not grow well in these mice, due to impaired tumour angiogenesis." (PMID 32921792, 2020). "Thus, we suggest that ANXA1 might influence the course of neoplasms by affecting interaction between cytokines." (PMID 32226026, 2020). "While pioglitazone showed its anti-inflammatory effects to be reliant on AnxA1, it is known pioglitazone has other effects that are PPARγ-independent, such as induction of migration of vascular smooth muscle cells and inhibition of proliferation of tumor cells." (PMID 33519451, 2020). "Even though annexin A1 was found to be relevant for development of several cancer types, no coherent paradigm for its role currently exists in the literature, and it is unknown whether this protein is a driver or passenger in the process of tumor progression." (PMID 31545917, 2019). "Indeed, regarding the down-modulated sequences in ANXA1 KO cells, we recognized miR-196a, miR-205, miR-10a, and miR-10b, which are known as oncogenic factor, inducing proliferation, migration, and invasion in several tumor models." (PMID 29986379, 2018). "Indeed, it has been reported that ANXA1 associated with NF-κB FPR2 activation by distinct ligands can trigger the GPCR-mediated signalling cascade to modulate cytokine signalling and tumour microenvironment, resulting in macrophage polarization and tumorigenesis." (PMID 29263330, 2017). "ANXA1 protein levels were also significantly higher in the HGG EVs compared with LGG EVs, which again may be associated with differences in tumour invasiveness between low- and high- grade tumours as well as the observed difference in IDH1 mutational status (Fig. 5b2)." (PMID 27770278, 2017). "Moreover, as a glucocorticoid-induced protein, ANXA1 might also be able to provide critical interference in the tumor stroma and its microenvironment cross-talk." (PMID 26137966, 2015).